TMEM74 (transmembrane protein 74)
Description:
Plays an essential role in autophagy. TMEM74-induced autophagy may involve PI3K signal transduction.
Synonyms: FLJ30668; NET36
Tractability: Antibody: UniProt predicts a signal peptide or a membrane-spanning region; its Gene Ontology location is reachable by antibodies, with medium confidence.
Gene: Protein-coding gene on chromosome 8 (108,606,850 to 108,787,624, reverse strand). Ensembl gene ENSG00000164841.
Subcellular location: Lysosome membrane; Cytoplasmic vesicle, autophagosome membrane
Subcellular location (Human Protein Atlas): Cytosol; Golgi apparatus
Gene Ontology:
Molecular function: protein binding; transmembrane transporter binding
Biological process: macroautophagy
Cellular component: autophagosome membrane; lysosomal membrane; plasma membrane
Genetic constraint (gnomAD): Loss-of-function variants: 13 observed, 19.28 expected, observed/expected ratio (o/e) 0.67, 90% interval 0.44 to 1.07. The upper end of that interval is the gene's LOEUF score, 1.07, which puts it in group 4 of 6, group 1 being the genes least tolerant of losing a copy. Missense variants: 372 observed, 397.1 expected, observed/expected ratio (o/e) 0.94, 90% interval 0.86 to 1.02. Synonymous variants: 159 observed, 156.26 expected, observed/expected ratio (o/e) 1.02, 90% interval 0.89 to 1.16.
Homologues: Orthologues: chimpanzee TMEM74 (100% identical), macaque TMEM74 (97% identical), dog TMEM74 (85% identical), pig TMEM74 (84% identical), mouse Tmem74 (77% identical), rat Tmem74 (77% identical), guinea pig TMEM74 (75% identical), rabbit TMEM74 (63% identical), tropical clawed frog tmem74 (45% identical). Paralogues in human: TMEM74B (33% identical).
Diseases named in the same sentence as TMEM74 in open-access papers:
TMEM74 is named in the same sentence as 15 diseases in open-access papers, as found by Europe PMC text mining. Sharing a sentence is not in itself a finding about the gene and the disease. The quoted sentences say what the papers report.
liver cancer (3 papers, 2021 to 2022). An epithelial or non-epithelial malignant neoplasm that arises from the liver. "The expression of ATIC, HDAC1, RHEB, SPNS1 and TMEM74 in liver cancer tissues was significantly higher than that in normal liver tissues." (PMID 34803509, 2021). "Interestingly, TMEM74 had been regarded as an oncogene in various cancers including liver cancer, lung cancer, breast cancer, colon cancer, cervical cancer, and hepatic carcinoma." (PMID 35186763, 2022).
breast carcinoma (2 papers, 2017 to 2022). "According to an analysis using KM plotter, it was found that the high expression of TMEM74 correlates tightly with the survival periods in the breast cancer and gastric cancer." (PMID 29048433, 2017).
Anxiety (1 paper, 2023). Intense feelings of nervousness, tension, or panic often arise in response to interpersonal stresses. "Our findings provide a novel rodent model of autism and anxiety comorbidity as well as new insights into the mechanisms of the pathogenesis of ASD and anxiety triggered by Tmem74 deficiency." (PMID 36690791, 2023). "Combining these experiments with optogenetic and pharmacological strategy revealed that TMEM74 in PL plays a critical role in the association with autism- and anxiety-like behaviors." (PMID 36690791, 2023). "Together, these data suggested that hyperactivity of glutamatergic Tmem74 deficit neurons in PL promote anxiety-like behaviors via the PL–BLA circuit." (PMID 36690791, 2023). "The restoration TMEM74 function reversed autism-related impairments and anxiety-like behavior, highlighting the central role of TMEM74 signal in the regulation of emotional state." (PMID 36690791, 2023). "Here, Tmem74-/- mice showed autism- and anxiety-like behaviors along with increased excitability of pyramidal neurons (PNs) in the prelimbic cortex (PL), which were reversed by Tmem74 re-expression and chemogenetic inhibition in PNs of the PL." (PMID 36690791, 2023). "We observed repetitive behaviors and social novelty preference impairments, together with cooccurring anxiety behaviors in Tmem74-/- mice, accompanied by the activation of c-Fos in the PNs of the PL." (PMID 36690791, 2023). "Our previous study reported that selective deletion of Tmem74 in the PNs of the BLA produced anxiety-like behaviors by elevating excitability of PNs in the BLA." (PMID 36690791, 2023). "In this context, we hypothesize that there is a relationship between PL Tmem74 deficits and autistic- and anxiety-like behaviors." (PMID 36690791, 2023). "To determine whether anxiety-like behaviors could be reversed by an enrichment of Tmem74 in Tmem74−/− mice, we performed OFT and EPM analyses." (PMID 36690791, 2023). "Moreover, our previous studies have suggested that Tmem74 deficits induce anxiety-like behavior." (PMID 36690791, 2023). "Recently, we reported that the functional coupling of TMEM74 and hyperpolarization-activated cyclic nucleotide-gated 1 (HCN1) channels in the pyramidal neurons of the BLA of Tmem74-/- mice regulated anxiety-like behaviors." (PMID 36690791, 2023). "Together, the data indicated that the Tmem74 deficit induced autism- and anxiety-like behaviors, but did not affect learning and memory in mice." (PMID 36690791, 2023). "To further determine whether the PL–BLA circuit is selective for anxiety-like behaviors, we suppressed PLPNs–BLA via NpHR optogenetic approach to examine whether the behavioral abnormalities could be rescued in Tmem74−/− mice." (PMID 36690791, 2023).
autism (1 paper, 2023). Persistent deficits in social interaction and communication and interaction as well as a markedly restricted repertoire of activity and interest as well as repetitive patterns of behavior. "Furthermore, from a multifunctional human stem cell platform database, we found that the mRNA level of Tmem74 was also remarkably decreased in human pluripotent stem cells (hPSCs) with early autism-related mutation genes." (PMID 36690791, 2023). "In autism-like behavior analyses, Tmem74−/− mice displayed increased repeated grooming phenotypes and numbers of marbles buried, both of which were alleviated by a gain of TMEM74." (PMID 36690791, 2023). "Moreover, we also identified the downregulation of TMEM74 in the PL of Shank3 knockout mice, implying that the Tmem74 deficit in PL guides autism-like behaviors." (PMID 36690791, 2023). "In addition, Tmem74−/− mice expressed repetitive behavior, social novelty impairment, and autism-like behaviors with high c-Fos expression in the PNs of the PL, and decreased TMEM74 protein levels appeared in the PLs of Shank3b−/− mice." (PMID 36690791, 2023). "To investigate the effect of Tmem74 in ASD, we performed autism-like behavioral analyses in Tmem74−/− mice." (PMID 36690791, 2023). "To verify the hypothesis that the hyperexcitability of PNs in PL guides autism-like behaviors, we expressed AAV-CaMKIIα-hM4D(Gi)-mCherry in the PL of 4-week-old WT and Tmem74−/− mice under intraperitoneal (i.p.)injection of clozapine-N-oxide (CNO, 1 mg/kg)." (PMID 36690791, 2023). "Together, these results strongly suggested that Tmem74 had a strong correlation with ASD and could be a novel autism-related gene." (PMID 36690791, 2023).
bladder cancer (1 paper, 2021). "While P4HB has been recently identified as a novel prognostic biomarker associated with overall survival of bladder cancer patients, TMEM74 has been shown to promote tumor cell survival by inducing autophagy." (PMID 33925460, 2021).
cardiomyopathies (1 paper, 2015). "TMEM74 plays a crucial role in autophagy induced by starvation and thus perhaps also in the manifestation of cancer, neurodegenerative diseases and cardiomyopathies." (PMID 26401333, 2015).
gastric cancer (1 paper, 2017). A primary or metastatic malignant neoplasm involving the stomach. "Additionally, the first progression survival of stage 3 gastric cancer likewise associates with the expression of TMEM74." (PMID 29048433, 2017). "Meanwhile, the gastric cancer belonging to diffuse types, intestinal and mixed types, their first progression survival periods also decline at the high expression of TMEM74." (PMID 29048433, 2017).
viral infection (1 paper, 2011). "Whether BNIP3 and TMEM74 are effective during viral infection is unknown, although they might both (co)-regulate cellular responses to viral infection through autophagy induction." (PMID 22174682, 2011).
tumor (7 papers, 2013 to 2024). "In conclusion, the results indicate tumor progression associates tightly with high TMEM74 expression." (PMID 29048433, 2017). "The relationship between TMEM74-induced autophagy and tumor cell survival has also been explored, and we generate a novel model concatenating autophagy and tumor cell fate." (PMID 29048433, 2017). "It was then assessed why TMEM74-triggered autophagy promotes tumor cell survival and determined the differences from other forms of ‘autophagy’, such as upstream signal-mediated autophagy." (PMID 29048433, 2017). "In this study, firstly, TMEM74 was shown to increase autophagic flux in diverse tumor cell lines and interact with ATG16L1 and ATG9A to induce autophagy." (PMID 29048433, 2017). "Considering the ultimate outcome of TMEM74-induced autophagy in tumor cells, TMEM74-triggered autophagy induces a pro-survival effect on tumor cells, particularly cells under metabolic stress, consistent with alteration of a series of signal pathways." (PMID 29048433, 2017). "In this study, TMEM74 was shown to increase the autophagic flux process in different tumor cell lines." (PMID 29048433, 2017). "Regarding tumor cell survival, the resistance to metabolic stress induced by TMEM74 overexpression was counteracted by ATG5, ATG7, ATG16L1, ATG3 and ATG10 deficiencies but not the BECN1 and ULK1." (PMID 29048433, 2017). "Five genes demonstrated complete loss or downregulation of expression in at least 20% of RCC tumours (GCM2 (80% of RCC), RGS7 (46.7%), TMEM74 (46.7%), NEFM (20%) and AEBP1 (20%))." (PMID 24034811, 2013). "After overexpressing TMEM74 in tumor cells, the proliferation ability of tumor cells was enhanced." (PMID 34746309, 2021). "After the confirmation of alternation of signal pathways, we next assessed whether TMEM74 promotes tumor cell survival." (PMID 29048433, 2017). "Intriguingly, TMEM74 itself can be downregulated through the autophagic process, which indicates that a potential self-regulatory loop exists so as to maintain an appropriate level of autophagy, avoiding excessive autophagy to commit tumor cells to death." (PMID 29048433, 2017). "In summary, TMEM74-induced autophagy may represent a novel autophagy pathway and a new model to substantiate the relationship between autophagy and tumor cell survival." (PMID 29048433, 2017). "The following discussion is separated into two parts that discuss the mechanism underlying TMEM74-induced autophagy and the hypothesis to explain why TMEM74-induced autophagy has a beneficial effect on tumor cell survival." (PMID 29048433, 2017). "Based on these results, TMEM74-induced autophagy promotes tumor cell survival." (PMID 29048433, 2017). "Next, we determined whether TMEM74-induced autophagy is credited with tumor cell survival." (PMID 29048433, 2017). "However, the mechanism by which TMEM74 stimulates autophagy and the impacts of TMEM74-induced autophagy on tumor cell survival remain unclear." (PMID 29048433, 2017). "In the mRNA group, ZIC5, C12orf75, C1QL1, TMEM74, and GNAZ were significantly upregulated in tumor tissues compared to the adjacent control; PZP and FAM65C were significantly downregulated compared to the adjacent control." (PMID 31156698, 2019). "Simultaneously, TMEM74 overexpression contributed to the increase in free GFP levels and the upregulation of SQSTM1 degradation in the three tumor cell lines." (PMID 29048433, 2017). "Although AMBRA1, ATG9B and TMEM74 suppression by Rapamycin signals defects in autophagy, evidence suggests the existence of a self-regulatory loop directing tumor cells to death rather than autophagy." (PMID 38276004, 2024). "TMEM74 is known to regulate autophagy and though it has not been implicated previously in RCC, it is interesting to note that the tumour suppressor activity of the VHL TSG has been linked to regulation of autophagy." (PMID 24034811, 2013).
tumor (continued). "The observed effects of Rapamycin on tumor suppression are likely to involve the autophagy process, evidenced by the inhibition of autophagy modulators (TGFβ1, RGS19 and AKT1), autophagosome biogenesis components (AMBRA1, ATG9B and TMEM74) and autophagy byproducts (APP)." (PMID 38276004, 2024).
cancer (6 papers, 2015 to 2022). A tumor composed of atypical neoplastic, often pleomorphic cells that invade other tissues. "High expression of TMEM74 significantly shortens the surviving periods of patients in several types of cancer." (PMID 33925460, 2021). "Further studies examining the properties of TMEM74 or similar molecules to understand autophagy will be important and may even represent targets for cancer therapy." (PMID 29048433, 2017). "Thus, TMEM74 may be a target for cancer therapy or a prognostic factor." (PMID 29048433, 2017).
TMEM74 also shares sentences with these, for which no sentence is quoted: colon cancer (2 papers); lung carcinoma (2); cervical cancer (1); hepatic carcinoma (1); neurodegenerative disease (1).